STAT2 (signal transducer and activator of transcription 2)
Diseases named in the same sentence as STAT2 in open-access papers (continued):
Sharing a sentence is not in itself a finding about the gene and the disease.
COVID-19 (33 papers, 2020 to 2026). A disease caused by infection with severe acute respiratory syndrome coronavirus 2. "Enhanced inflammatory response in the basal state and during COVID-19 in individuals with STAT2 deficiency." (PMID 36976641, 2023). "This case study effectively demonstrated the identification of a novel BP variant in STAT2 from a life-threatening COVID-19 patient and the experimental validation of its biochemical consequences." (PMID 36306325, 2022). "Absolute cell-type deconvolution analysis demonstrated higher positive enrichment score for classical monocytes, basophils, CD8EM cells, and non-Vδ2 TCR-γδ T cells in the STAT2-deficient patient than in the control, both during acute COVID-19 illness and outside of infectious/inflammatory episodes." (PMID 36976641, 2023). "This patient did not experience severe inflammation at the time of COVID-19, but our data nevertheless highlight an enhancement of inflammatory cascades (TNF/NF-κB and IL-6/JAK/STAT3) in STAT2 deficiency, both in the basal state and during acute COVID-19, mediated predominantly by neutrophils." (PMID 36976641, 2023). "In support of this hypothesis, type I IFN scores were strongly correlated to STAT2 levels (ρ = 0.91, P = 6.8 × 10−20), for which our group previously demonstrated a simultaneous antiviral and pathogenic in vivo role in a COVID-19 hamster model." (PMID 37217661, 2023). "The SpliceAI, MMSplice, and CADD scores could provide additional reference but should not be fully relied upon, particularly when evaluating newly identified BP variants (see our case study of a STAT2 variant in a critical COVID-19 patient)." (PMID 36306325, 2022). "Our timely recruitment of BPHunter to screen our COVID-19 cohort directly led to the identification of a novel and deleterious BP variant in the STAT2 gene from a patient with life-threatening COVID-19, which was immediately tested experimentally to demonstrate its biochemical consequences." (PMID 36306325, 2022). "Neutrophils were the only cells for which the positive enrichment score in the STAT2 patient was much higher during acute mild COVID-19 than in the basal state or in a healthy control." (PMID 36976641, 2023). "Here, HSCT, PSMB9, STAT2, and TNFSF13B were identified as common risk genes of AF and COVID-19 patients." (PMID 38025532, 2023). "Genes impacting mitochondrial function include 31 of 37 in mitochondrial DNA and nuclear genes encoding mitochondrial proteins, including ten EDS-related (NDUFA-11/S3, OPA1, TYMP, etc.)and three COVID-19-related (STAT2, TLR3, NDUFAF7) genes." (PMID 37504295, 2023). "In this sense, IFN polymorphisms or polymorphisms of the molecules in charge of signaling for their production, such as IRF3, IRF7, TICAM1, TBK1, and STAT2, have also been related to poor prognosis of COVID-19 patients." (PMID 35062298, 2022). "STAT1 and STAT2 have higher activity in moderate patients than severe patients, suggesting a possible delay in the interferon response in severe COVID-19 patients." (PMID 34603282, 2021). "However, in this work, the associations between the STAT2 variant 12-56744928-GA and the TLR-3 variant 12-56744928-GA with severe COVID-19 and mild COVID-19, respectively, were detected." (PMID 35062298, 2022). "One of the most strongly affected TFs is STAT2, together with STAT6, which could be linked to the aberrant IFN signaling in monocytes in COVID-19." (PMID 36443794, 2022). "To confirm these observations, we looked at the specific expression of Stat genes, including the IFN-associated signal transducers and activators of transcription 1 (STAT1) and STAT2, which were both significantly underrepresented in patients with COVID-19 compared to patients with influenza." (PMID 33187979, 2020). "Finally, we found that STAT2 was mainly expressed in AF and COVID-19 patients, respectively." (PMID 38025532, 2023).
COVID-19 (continued). "Despite their different effects on COVID-19 prognosis and their use of distinct receptor complexes, in cells, both type I and type III IFNs induce activation of STAT1, STAT2, and STAT3, as well as a similar subset of IFN-responsive genes." (PMID 40980495, 2025). "We found that IRF7 is significantly up-regulated in both AD and COVID-19 and, together with STAT genes (such as STAT2), are located in the core of the signaling transduction module." (PMID 38257800, 2024). "For example, compared to activated STAT2 and KLF5 in mild/moderate goblet cells, SPDEF, ELF3, XBP1, and NR2F6 were found activated in patients with severe COVID-19." (PMID 37936693, 2023). "Among them, the level of STAT2 in AC16 cells was most affected by pseudovirus treatment, which indicated the COVID-19 vulnerability of human species." (PMID 38025532, 2023). "The dysregulation of all three types of interferons (I, II, III) in COVID-19 patients reveals the effect of infection on the common genes of these cytokines (such as STAT1, STAT2)." (PMID 36405703, 2022). "During COVID-19, SARS-CoV-2 nucleocapsid (N) protein binds to STAT1/STAT2 with the downstream kinases and inhibits their phosphorylation." (PMID 34603282, 2021). "For example, RFX2 and RFX3 showed high activity in ciliated cells regardless of disease severity, while XBP1, NR2F6, SPDEF, and ELF3 were preferentially activated in goblet cells in patients with severe COVID-19, and KLF5 and STAT2 were coactivated in patients with mild/moderate COVID-19." (PMID 37936693, 2023). "As for the four common genes from WGCNA modules (HCST, PSMB9, STAT2, TNFSF13B), the HCST showed significant differences between the control/AF group and the healthy/COVID-19 group, while the STAT2 showed significant differences between the healthy and COVID-19 groups." (PMID 38025532, 2023). "All signaling molecules of the IFN-I downstream pathway and IRFs (i.e., JAK-1, TYK-2, STAT-1, STAT-2, IRF-3, and IRF-7) showed very reduced expression levels in COVID-19 patients with the severe condition compared to healthy individuals at both RNA and protein levels." (PMID 35842705, 2022). "Furthermore, STAT1 (21,435th → 32nd), STAT2, EGFR, and IRF9 (2455th → 36th) are involved in interferon signaling and have been suggested in numerous COVID-19 studies." (PMID 36291657, 2022). "It has also been reported that SRCs contribute to HIV reactivation via mTOR and STAT2, and MACROH2A1-SRC family axis may regulate the inflammatory pathogenesis of COVID-19." (PMID 36451245, 2022). "Neither EIF2AK2 nor IFN-responsive transcription factors such as STAT1 and STAT2 were expressed within SARS-CoV-2 RNA+ cells from participants who developed severe COVID-19." (PMID 34352228, 2021). "In goblet cells, STAT2 and KLF5 were highly activated and upregulated in many genes with mild/moderate COVID-19, such as ISGs (PARP14 and IFI44L), whereas ELF3, SBP1, NR2F6, and SPDEF were preferentially activated in severe COVID-19 to regulate the expression of their targets." (PMID 37936693, 2023). "Our results reveal the importance of STAT2-dependent interferon responses in the pathogenesis and virus control during SARS-CoV-2 infection and may help rationalizing new strategies for the treatment of COVID-19 patients." (PMID 33203860, 2020). "We found that the expression of STAT1, STAT2, and IRF1 was indistinguishable among cells from control WHO 0, control WHO 7–8, and COVID-19 WHO 6–8 participants." (PMID 34352228, 2021). "Intriguingly, despite the absence of autoantibodies directed at type I interferons, nearly all participants who developed severe COVID-19 failed to induce STAT1, STAT2, IRF1, and IRF9 expression (among other IFN-stimulated genes)." (PMID 34352228, 2021).
COVID-19 (continued). "Wild type Syrian hamsters and knockout hamsters for signal transducer and activator of transcription 2 (STAT2−/− lacking type I and III interferon signaling) and interleukin 28 receptors (IL28r−/− lacking IFN type III signaling) were reported as models for COVID-19." (PMID 33023604, 2020).
breast carcinoma (18 papers, 2015 to 2024). "High STAT2 mRNA level showed a null association with OS (HR =0.82 (0.6–1.12), P=0.22) in breast cancer patients." (PMID 29326301, 2018). "In conclusion, our results suggest that high mRNA expression of all the individual STATs, except STAT1 and STAT2, are significantly associated with favorable OS in breast cancer patients, especially for the high pathological grade." (PMID 29326301, 2018). "High STAT2 expression is associated with a favorable OS in melanoma and gastric cancer patients and is correlated with a better relapse-free survival in breast cancer patients." (PMID 35207629, 2022). "Moreover, STING expression was also positively correlated with the expression of the IFN‐I signaling genes ISG15, STAT1 and STAT2 in breast cancer MSCs." (PMID 38638003, 2024). "Interestingly, IFITM1 overexpression has been shown to enhance the aggressive phenotype of SUM149 inflammatory breast cancer cells in a signal transducer and activator of transcription 2 (STAT2)-dependent manner." (PMID 36230929, 2022). "Our results indicate that individual STATs, except STAT1 and STAT2, may act as a favorable prognostic biomarker in breast cancer." (PMID 29326301, 2018). "STAT2, STAT4, STAT5a, STAT5b, and STAT6 had significantly favorable effect on RFS of breast cancer patients, but STAT1 had significant worse effect on RFS; STAT5b had significant favorable effect on PPS, while, STAT2 had significant worse effect on PPS for breast cancer patients." (PMID 29326301, 2018). "In breast cancer, however, the suppression of IRF9 or STAT2 transcription induces resistance to the PARP inhibitor." (PMID 39062738, 2024). "In human breast tumor tissues, mRNA levels of EIF2Ak2, USP18, DDX58, RBL2, STAT2, PGR, S1000A9, and CCND1 were significantly higher in ER+- than in ER--breast cancer tissues." (PMID 29416786, 2018). "Further, upregulation of ISGs like STAT1, STAT2, or IRF9 is known to promote cancer resistance to chemotherapy and radiotherapy as demonstrated in human head and neck squamous cell carcinoma and breast cancer." (PMID 27533247, 2016). "Real-time PCR and Western blot analyses were used to assess mRNA and protein levels of IFITM1, PLSCR1, STAT1, STAT2, and IRF-7 in AI-resistant MCF-7:5C breast cancer cells and AI-sensitive MCF-7 and T47D cells." (PMID 25588716, 2015). "Initially, we evaluated the expression of IFN-signaling proteins (STAT1 (Y701), STAT1, STAT2, IRF9) and IFN-stimulated proteins that induce an antiviral state (OAS1 and MxA) in MCF7/pS, MCF7/pR, 231/pS and 231/pR breast cancer cells in the absence or presence of palbociclib." (PMID 31100952, 2019). "Our results indicate that STATs family play a significantly prognostic role in breast cancer patients and individual STATs, except STAT1 and STAT2, and may be a favorable prognostic biomarker in breast cancer." (PMID 29326301, 2018). "Similar to STAT2, the evidence of STAT4 expression in breast cancer patients was limited." (PMID 29326301, 2018). "ISGylation of STAT1 and STAT2 mediate clustering and nuclear relocalization of STAT1 and STAT2 within IFN-induced PML bodies and synergistically promotes the production of chemokine-receptor ligands to attract cytotoxic T cells, thereby suppressing murine breast cancer growth and metastasis." (PMID 36319753, 2022). "Further studies are needed to validate these findings in other inflammatory and non-inflammatory breast cancer cell lines and to assess the mechanism of action by which RhoC expression may modulate STAT2 expression." (PMID 34513691, 2021). "Thus, cells with increased STAT2 and pSTAT2 upon stimulation with IFN-α were more resistant to IFN-α-driven transwell invasion inhibition, and furthermore RhoC expression affects STAT2 and pSTAT2 expression in different ways in inflammatory and non-inflammatory breast cancer cells." (PMID 34513691, 2021).
breast carcinoma (continued). "Although STAT1 and STAT2 are not hit genes by themselves, TFs from the STAT family have established connections to breast cancer and skin." (PMID 38632500, 2024). "In the breast cancer cell line MCF7, which does not originate from TNBC and was still able to respond to IFN treatment with reduced proliferation, the overexpression of IRF9, but not STAT1 or STAT2, increased the resistance of cells against the chemotherapeutic drug paclitaxel." (PMID 33430083, 2021).
melanoma (18 papers, 2011 to 2025). A malignant, usually aggressive tumor composed of atypical, neoplastic melanocytes. "STAT2 protein levels have been shown to be higher in melanoma than in normal skin and to correlate with increased melanoma cell proliferation." (PMID 37408506, 2023). "Knocking down IRF9 or STAT2 in melanoma cell lines A375 and SK-MEL-28 induces GSDME-dependent pyroptosis and restores sensitivity to BRAFi." (PMID 37373523, 2023). "Acting downstream to these signals and being positioned basically on each of the identified SEs, STAT2 (and likely other members of this family) candidates to be a master regulator of the metastatic switch in melanoma." (PMID 37408506, 2023). "In line with this evidence, STAT2 and its companion IRF9 were found to mediate resistance to BRAFi and to be associated with amoeboid phenotype in melanoma." (PMID 37408506, 2023). "Several target genes of miR-653-5p, such as signal transducer and activator of transcription 2 in neuroblastoma as well as retinoic acid induced 14 in melanoma, have been identified." (PMID 34866540, 2021). "In summary, the important finding is that STAT2 stability regulation is directly involved in melanoma cell proliferation." (PMID 32973222, 2020). "Our research group reported that STAT2 protein levels are higher in melanoma tissues than in normal skin tissues." (PMID 32973222, 2020). "Our recent studies have demonstrated that signal transducer and activator of transcription 2 (STAT2) stability regulation plays an important role in melanoma formation." (PMID 32973222, 2020). "A recent publication provided further understanding of the physiological relevance of STAT2 protein levels in human cancers, especially melanoma proliferation." (PMID 32973222, 2020). "Melanoma cell proliferation is also correlated with STAT2 protein levels, indicating that STAT2 activity plays an essential role in melanoma promotion." (PMID 32973222, 2020). "Deregulated JAK3 and RNase L pathways in LNCaP prostate cancer cells, defective STAT1 and STAT2 activation in fibrosarcoma and melanoma cells and down-regulated IFNAR in high grade bladder cancer have all been reported to disable the innate immune signaling." (PMID 22194884, 2011). "Targeting IRF9/STAT2 may offer a promising strategy to prevent melanoma resistance to BRAFis by regulating pyroptosis, leading to the durable regression of melanoma in an immune-mediated manner." (PMID 37373523, 2023). "Moreover, several experimental data have strongly suggested that STAT2 is involved in carcinogenesis, including prostate cancer, renal cancer, leukemia, lymphomas, skin cancer, and melanoma." (PMID 32973222, 2020). "Moreover in literature some papers are already reporting data about IFNα immunotherapy and STAT2 status in melanoma and in other type of diseases." (PMID 31159827, 2019). "Targeting IRF9/STAT2 may prevent BRAFis resistance in melanoma by inducing pyroptosis." (PMID 39802949, 2024). "Moreover, the sustained activation of type I interferon signalling in response to IFNβ mediated by the Stat1/Stat2/IRF9 complex enhances the round amoeboid phenotype in melanoma cells, whereas its downregulation by various approaches promotes the mesenchymal invasive phenotype." (PMID 32872349, 2020). "Importantly, a Kaplan–Meier analysis indicated that high levels of STAT2 protein may reduce the 5-year survival probability for melanoma patients." (PMID 32973222, 2020). "PRELPhigh melanoma cells express increased levels of NLRC5 as well as selected IFN-γ signal transduction molecules, e.g., IRF1, IRF5, STAT1 and STAT2." (PMID 37730606, 2023). "As was observed for melanoma cells, IFNγ treatment of Ptpn2 knockout CT26 and MC38 cells enhanced the expression of the IFNγ response genes Cxcl1, Ccl5, Stat1, Stat2, Stat3, Irf1, Pd-l1, Tap1, and Casp8, compared with IFNγ-treated control cells." (PMID 36968224, 2023). "IRF9 and STAT2, which are part of the Jak-STAT pathway, play a major role in BRAFi resistance in melanoma." (PMID 37373523, 2023).
melanoma (continued). "The IFN-γ -JAK1/JAK2-STAT1/STAT2/STAT3-IRF1 axis, a key regulator of IFN-mediated PD-L1 expression in melanoma cells, seems to be a good therapeutic option." (PMID 33672515, 2021). "High level of IFN-β activates STAT1, STAT2 and STAT3 to facilitate cellular dormancy in tumor-repopulating melanoma cells." (PMID 30546090, 2019).
hepatocellular carcinoma (16 papers, 2011 to 2026). A malignant tumor that arises from hepatocytes. "Transmembrane protein 147 (TMEM147) upregulates DHCR7 via signal transducer and activator of transcription 2 (STAT2) in hepatocellular carcinoma (HCC), elevating 27HC and GPX4, which strengthens ferroptosis resistance and metastasis." (PMID 41596341, 2026). "STAT3 gene is highly expressed in hepatocellular carcinoma cells, and regorafenib (Stivarga), a drug targeting STAT2 for the treatment of hepatocellular carcinoma, has been identified as a second-line oral agent." (PMID 35927985, 2022). "To this end, we compared the expression of twelve genes either linked to the induction of innate immunity (STAT1, STAT2, PKR) or IFN effector genes (OAS1/2, IFIT1–3, RSAD2, MX1, TRIM14, ISG15) in HCV-infected hepatoma cells and mature iHLCs." (PMID 29497123, 2018). "In terms of tumors, N4BP3 is able to promote the expression of STAT2 by interacting with KAT3B, thereby promoting the angiogenesis in hepatocellular carcinoma, making N4BP3 a potential therapeutic target for hepatocellular carcinoma." (PMID 39420190, 2024). "Other studies have shown that Sp1, IRF1 and IRF2 can bind to the APOL1 promoter in hepatoma cells, and IRF1, IRF2 and STAT2 to the APOL1 promoter in podocytes and endothelial cells." (PMID 37924378, 2024). "We establish, based on quantitative measurements obtained for the hepatoma cell line Huh7.5, an ordinary differential equation model for IFNα signal transduction that comprises the feedback regulators STAT1, STAT2, IRF9, USP18, SOCS1, SOCS3, and IRF2." (PMID 32696599, 2020). "It has also been observed that hepatoma cells are capable of forming STAT2/STAT6 heterodimers in response to IFN type I; moreover, B cells stimulated with IFNα induce the formation of a STAT2/STAT6/IRF9 complex." (PMID 33076315, 2020). "Given their importance in the innate antiviral response and the connection between HCV and hepatocellular carcinoma, we examined the expression of several key mediators of the host antiviral response, STAT1, STAT2, and NF-κB." (PMID 31374104, 2019). "In hepatocellular carcinoma, IFIT3 could bind signal transducer and activator of transcription 1 (STAT1) and STAT2 to enhance STAT1–STAT2 heterodimerization and nuclear translocation upon IFN-α treatment, thus promoting IFN-α effector signalling." (PMID 34418997, 2021). "Similarly, it was reported that HCVc inhibits nuclear import of STAT1 in transiently transfected HuH-7 hepatoma cells, and inhibits both STAT1 and STAT2 in human osteosarcoma-derived cell lines that express HCVc37." (PMID 27786268, 2016). "However, the authors inferred this STAT2-dependent pathway was liver-specific since they could not carry these observations into cells other than human hepatoma cells." (PMID 21379341, 2011).